EGFR (epidermal growth factor receptor)
Diseases named in the same sentence as EGFR in open-access papers (continued):
Sharing a sentence is not in itself a finding about the gene and the disease.
lung sarcomatoid carcinoma (2 papers, 2022 to 2025). A rare, aggressive, poorly differentiated, non-small cell lung carcinoma characterized by the presence of a sarcomatoid component often associated with giant cell differentiation. "There are conflicting reports on the prevalence of EGFR mutation in sarcomatoid carcinoma of the lung." (PMID 36200011, 2022).
lymphopenia (2 papers, 2017 to 2021). Reduction in the number of lymphocytes. "The application of EGFR antagonists, and thus the suppression of Tregs function during this immune replenishment phase following CT-induced lymphopenia, may have the capacity to substantially improve the reactivation of anti-tumor immune responses and efficacy of CT." (PMID 28970798, 2017).
malignant peripheral nerve sheath tumor (2 papers, 2019 to 2022). Malignant peripheral nerve sheath tumor (MPNST) is a rare and often aggressive soft tissue sarcoma occurring in a wide range of anatomical sites. "Malignant peripheral nerve sheath tumors (MPNSTs), driven in part by hyperactive Ras and EGFR signaling, are often incurable." (PMID 36221123, 2022).
mastocytosis (2 papers, 2010 to 2024). A clonal myeloproliferative neoplasm characterized by the proliferation and accumulation of neoplastic mast cells in one or multiple organs or organ systems. "Proximal airway neutrophilia, lymphocytosis and mastocytosis was clearly present 6-18 hour post exposure, associated with an up-regulation of redox sensitive signalling and EGFR pathways in the bronchial mucosa together with increased GSH concentrations in BAL fluid." (PMID 20727160, 2010).
measles (2 papers, 2022). A highly contagious viral infection caused by the measles virus. "By establishing EGFR as an integral regulator of oncolytic VSV growth, it is possible that EGFR status could influence patient response to treatment regimens employing VSV and potentially other RNA-based OVs like measles and NDV." (PMID 35572196, 2022).
memory impairment (2 papers, 2021 to 2022). "The higher serum Cathepsin D, IgE, EGFR, MMP-9, vWF, haptoglobin, and p-Tau181 levels were associated with severity of memory impairment (as indicated by lower MMSE and MoCA scores, and higher ADL, CDRglobal, and CDRsob scores)." (PMID 35769604, 2022). "Based on these findings, they suggested that EGFR may be a therapeutic target for the treatment of amyloid- β-induced memory impairment." (PMID 33941241, 2021).
meningeal tumors (2 papers, 2014 to 2021). "The present study is an attempt to evaluate the role of EGFR vIII in meningeal tumors by immunohistochemical and flow cytometric methods." (PMID 34582442, 2021).
metaplastic breast carcinoma (2 papers, 2014 to 2023). A group of invasive breast carcinomas characterized by the presence of an adenocarcinomatous component which is admixed with a dominant component that is composed of squamous cells, spindle cells, or mesenchymal cells. "EGFR was overexpressed in metaplastic breast cancer, and EGFR inhibitor was potential therapeutic agent for metaplastic breast cancer with 7p11.2 amplification." (PMID 37719859, 2023). "Thus, gefitinib may be a promising agent used for the treatment of metaplastic breast carcinoma with frequent expresses of EGFR." (PMID 24498372, 2014).
mood disorder (2 papers, 2024 to 2025). A cognitive disorder a disturbance in which the person's mood is hypothesized to be the main underlying feature. "Understanding the intricate relationship between EGFR activation, neuroinflammation, and the modulation of neurotrophic factors may provide valuable insights into the underlying mechanisms of mood disorders." (PMID 40611827, 2025).
mood disturbances (2 papers, 2023 to 2025). "These 15 features were selected by the CWGB algorithm, with the number of episodes of mood disturbances, microbleeds and lacunes having the larger positive effects on the risk prediction and an EGFr mutation location in domains 7 to 34 being the only feature with a negative effect on the risk." (PMID 38105268, 2023). "For patients with EGFR or ALK mutations, we adopted the MMSE assessment scale, EORTC QLQ-C30 scale, and DT scale to evaluate the relationship between changes in cognitive function during targeted treatment and QoL and psychological distress and cognitive function’s impact on treatment outcomes." (PMID 40966684, 2025).
mucinous ovarian cancer (2 papers, 2023 to 2025). An invasive malignant neoplasm that arises from the ovary and is characterized by the presence of malignant epithelial cells that contain intracytoplasmic mucin and may resemble the epithelial cells of the endocervix or gastrointestinal tract. "A study found that mucinous ovarian cancer (MOC) with infiltrative invasion was more often positive for CK5/6, CD24, and EGFR, suggesting that these markers may be linked to the aggressive features of this invasion pattern." (PMID 40231265, 2025).
nasal polyp (2 papers, 2016 to 2023). "To investigate the link between specific EGFR mutations and SIP development, we established organotypic raft culture system using nasal polyp-derived immortalized NP2 (iNP2) cells expressing EGFR exon 20 mutants or an exon 19 mutant, and SIP-derived iIP4 cells harboring P772_H773insPYNP mutation." (PMID 37891239, 2023). "The current study investigates the expression profiles of EGF, EGFR and ERBB4 in patients with nasal polyps (NP), and their response to glucocorticosteroid (GC) treatment." (PMID 27285994, 2016).
nematode infection (2 papers, 2023). "EGFR and its ligands play important roles in resistance to nematode infection." (PMID 36768605, 2023). "In addition, Amphiregulin binds to EGFR, is essential for the production of the key cytokine IL-13 and enhances resistance to nematode infection." (PMID 36768605, 2023). "Our pilot trials suggest that this molecule or its cleavage products bind epidermal growth factor receptor (EGFR), disrupt normal signalling and modulate the immune response to nematode infection." (PMID 36768605, 2023).
nephritis (2 papers, 2019 to 2022). Inflammation of renal tissue. "To determine the effect of glucocorticoids on EGFR/STAT3 signaling in anti-GBM nephritis, we performed immunohistochemical staining of phosphorylated EGFR and STAT3 in the renal biopsies of the patients with (n = 22) and without (n = 12) glucocorticoids treatment." (PMID 35223886, 2022).
Noonan-like syndrome (2 papers, 2012 to 2023). "It has been proposed that overexpression of the Shoc2 mutant with the S2G substitution (serine 2 is mutated to glycine), found in Noonan-like syndrome patients, results in N-myristoylation and targeting of this Shoc2 mutant to the plasma membrane, and enhances EGFR-dependent ERK1/2 activity." (PMID 22606262, 2012). "It has been demonstrated that pathogenic germline variants in the CBL gene impact the ubiquitylation and migration of EGFR, resulting in loss of downregulation function of the CBL protein in the RAS-MAPK pathway, which leads to Noonan syndrome and other RASopathies." (PMID 37711606, 2023).
NUT carcinoma (2 papers, 2018 to 2021). "High EGFR (60%) expression has been reported in the non-squamous areas in a NUT carcinoma case." (PMID 34898574, 2021).
ocular toxoplasmosis (2 papers, 2019 to 2021). Ocular toxoplasmosis is an infection in the eye caused by the parasite, Toxoplasm a gondii. "Studies in transgenic mice that express a dominant-negative (DN) mutant of EGFR that impairs EGFR autophosphorylation and EGFR transactivation revealed the importance of manipulating host cell signaling in the development of cerebral and ocular toxoplasmosis." (PMID 34179003, 2021). "In summary, our studies identified EGFR as an important modulator for the development of cerebral and ocular toxoplasmosis and uncovered EGFR as regulator of neural tissue invasion by T. gondii." (PMID 30679495, 2019). "Blockade of EGFR led to spontaneous killing of T. gondii within endothelial cells, reduction in the foci of infected endothelial cells in vivo, decreased parasite load in the brain and retina as well as protection against cerebral and ocular toxoplasmosis." (PMID 30679495, 2019).
odontogenic cyst (2 papers, 2020 to 2021). A cyst in the jaw that arises from tissues of tooth development. "The immunolocation of EGFR in odontogenic epithelium may therefore be associated with the origin of odontogenic cysts and tumors." (PMID 33374329, 2020).
Olmsted syndrome (2 papers, 2023 to 2025). A hereditary palmoplantar keratoderma characterized by the combination of bilateral mutilating transgredient palmoplantar keratoderma and periorificial keratotic plaques. "Treatment of patients with Olmsted syndrome (gain-of function mutation Gly573Cys) by the EGFR inhibitor erlotinib led to positive results a rapid significant improvement in the symptoms of palmoplantar keratoderma (PPK), including pain and itch." (PMID 37239947, 2023). "The symptoms of Olmsted syndrome are thought to be related to the TRPV3/EGFR signaling pathway." (PMID 37239947, 2023).
oral lichen planus (2 papers, 2014 to 2024). Oral lichen planus is a chronic inflammatory oral condition of unknown aetiology characterized by T-cell-mediated chronic immune response and abnormal epithelial keratinization cycle. "Key words:Oral lichenoid disease, oral lichen planus, oral lichenoid lesion, oral carcinogenesis, EGFR." (PMID 24880441, 2014).
papillary adenoma (2 papers, 2015 to 2024). An adenoma characterized by the presence of papillary epithelial patterns. "For patients with EGFR-mutated papillary adenomas, further study is needed to determine whether extended resection or postoperative treatments are needed." (PMID 38902753, 2024). "The absence of EGFR and K-ras gene mutations in papillary adenoma might also be helpful for differential diagnosis." (PMID 26474555, 2015).
phyllodes tumor of the breast (2 papers, 2016 to 2023). "The undertaken PCA analysis recognized that age and histological types are associated with expression status of CD 10 and EGFR in breast phyllode tumors." (PMID 38974258, 2023). "On the basis of PCA analysis it could be assumed that patient's age and histological type of tumor have significant association with CD10 and EGFR expression in phyllode breast tumors." (PMID 38974258, 2023).
primitive neuroectodermal tumor (2 papers, 2014). A malignant neoplasm that originates in the neuroectoderm. "A gross total resection was performed and the pathology showed GBM with primitive neuroectodermal tumor (PNET) component (MGMT promoter unmethylated, EGFR not amplified, 1p/19q co-deletion negative)." (PMID 24884522, 2014).
pulmonary blastoma (2 papers, 2012 to 2022). A malignant neoplasm of the lung composed of tubular structures and immature mesenchymal elements, which may differentiate towards skeletal and smooth muscle, cartilage or a combination of muscle and cartilage. "From our findings we conclude that similar to pulmonary blastoma pulmonary carcinosarcoma may harbour MDM2 and lack EGFR mutations." (PMID 23006472, 2012).
purpura (2 papers, 2019 to 2024). A small blood vessel hemorrhage into the skin and/or mucous membranes. "Although purpura associated with EGFR inhibitors tends to resolve within a few weeks of initiating antimicrobial therapy, our case required 2 months of doxycycline treatment." (PMID 39881923, 2024). "Conversely, many cases of EGFR inhibitor-associated purpura, including ours, have improved with antimicrobial therapy without the halt of chemotherapy or the initiation of oral steroids." (PMID 39881923, 2024). "On performing a literature search of PubMed for the period up to 2016 using the keywords LCV, purpura, and renal toxicity related to anti-EGFR antibody, we identified several cases of LCV associated with purpura." (PMID 30646927, 2019). "Patients with both purpura and renal toxicity caused by anti-EGFR antibody are rather rare." (PMID 30646927, 2019). "For EGFR inhibitor-induced purpura, either the inhibitor or inflammatory cells activated by it may directly damage vascular endothelial cells, leading to purpura." (PMID 39881923, 2024). "However, there are few reports of purpura induced by anti-epidermal growth factor receptor antibody." (PMID 30646927, 2019). "However, there are few reports of purpura induced by anti-epidermal growth factor receptor (EGFR) antibody." (PMID 30646927, 2019). "Additionally, purpura development may involve increased vascular tone and permeability due to inhibited EGFR in perivascular smooth muscle." (PMID 39881923, 2024). "Purpura induced by EGFR inhibitors appears regardless of follicle regions, whereas papulopustular eruption typically arises from hair follicles." (PMID 39881923, 2024). "Typically, purpura induced by EGFR inhibitors can occur regardless of the follicular region." (PMID 39881923, 2024).
radicular cysts (2 papers, 2020 to 2022). "In a study done by Shear, expression of the EGFR marker was reported in the epithelium of OKCs and dentigerous as well as radicular cysts." (PMID 33374329, 2020).
respiratory infection (2 papers, 2019 to 2025). "EGFR signaling has been shown to support tissue regrowth during respiratory infection." (PMID 40496017, 2025).
retinal detachment (2 papers, 2015 to 2022). An eye emergency condition which may lead to blindness if left untreated. "Minor Müller cell trauma has been extensively studied in retinal detachments where it results in an upregulation of epidermal growth factor receptor (EGF-R)." (PMID 25695062, 2015).
skin aging (2 papers, 2023 to 2024). The gradual irreversible changes in structure of skin that occur as a result of the passage of time.. "And JUN, TGF, and EGFR signaling pathways have been reported to influence blue-light-induced skin aging." (PMID 37626816, 2023).
Skin ulcer (2 papers, 2018 to 2022). A discontinuity of the skin exhibiting complete loss of the epidermis and often portions of the dermis and even subcutaneous fat. "Cathelicidins can also contribute to skin ulcer repair by inducing keratinocyte migration via transactivation of the epidermal growth factor receptor." (PMID 30072966, 2018). "Tyrosine kinase inhibitors, mainly epidermal growth factor receptor blockers may enhance skin ulcerations, vascular endothelial growth factor inhibitors have the risk of thromboembolic events and fistula formations, therefore do not use them in case of malignant fungating wounds." (PMID 35267512, 2022).
sleep disorder (2 papers, 2020 to 2025). A change from the patient's baseline sleeping pattern, in the hours slept and/or an alteration/dysfunction in the stages of sleep. "In humans, variation in genes that participate in EGFR signaling and 5-HT signaling have been implicated by genome-wide association studies in human sleep traits and sleep disorders." (PMID 33337320, 2020).
small intestinal tumors (2 papers, 2013 to 2022). "A high percentage of small intestinal tumors reportedly express epidermal growth factor receptor and vascular endothelial growth factor, suggesting that molecular-targeted therapy may improve the outcomes." (PMID 24649253, 2013).
squamous cell tumors (2 papers, 2011 to 2016). "EGFR mutations were also more common in adenocarcinomas (35.7%) than squamous cell tumors (9.9%) and tumors of other histology (22.4%)." (PMID 27294665, 2016). "None were found in patients with squamous cell tumours or in patients harbouring EGFR mutations." (PMID 21949883, 2011).
T-cell leukemia (2 papers, 2013 to 2021). A malignant disease of the T-lymphocytes in the bone marrow, thymus, and/or blood. "The median IC50 of the NOTCH1 mutant type cancer cell lines was smaller than that of the wild-type, indicating that an EGFR inhibitor (gefitinib) has potential therapeutic effects for T-cell leukemia with a NOTCH1 mutation." (PMID 33627666, 2021).
Thrombocytosis (2 papers, 2016 to 2020). Increased numbers of platelets in the peripheral blood. "In our study, only one of nine patients with p-Leuko/Thrombocytosis had an EGFR mutation positive status." (PMID 27866514, 2016). "NSCLC patients who had positive EGFR mutations were not more likely to present with Leuko/thrombocytosis compared to those with who did not have EGFR mutations (1/5 vs 8/55 respectively)." (PMID 27866514, 2016). "Presence of EGFR mutation as an individual risk factor for leuko/thrombocytosis were not assessed due to small sample size." (PMID 27866514, 2016). "Survival comparisons between EGFR mutation positive patients with and without p-Leuko/Thrombocytosis could not be examined statistically due to small sample estimates." (PMID 27866514, 2016). "Similarly, survival comparisons could not be made between EGFR mutation positive patients with and without leuko/thrombocytosis due to small sample size." (PMID 27866514, 2016).
thymic squamous cell carcinoma (2 papers, 2020 to 2023). "Herein we report a case of an advanced thymic squamous cell carcinoma patient harboring EGFR exon 20 insertion who had previously received multiline therapy, including chemotherapy, radiotherapy as well as antiangiogenic therapy." (PMID 32997432, 2020). "We completed imaging as well as genomic profiling using next‐generation sequencing (NGS) and supplemented the diagnosis with Masaoka‐Koga stage IVB thymic squamous cell carcinoma accompanied by EGFR exon 20 insertion, with a negative PD‐L1 expression." (PMID 32997432, 2020).
tonsil cancer (2 papers, 2010 to 2023). A primary or metastatic malignant neoplasm that affects the tonsil.
trichomegaly (2 papers, 2024 to 2025). "Consistent with our results, A study describing ocular toxicities of EGFR inhibition in patients with malignancy noted that all cases of trichomegaly occurred within 3–5 months after starting therapy." (PMID 39739702, 2024). "However, trichomegaly and trichiasis were reported simultaneously, and times to MT were not stratified to therapy as both TKIs and monoclonal antibodies were used to inhibit EGFR." (PMID 39739702, 2024).
upper tract urothelial carcinoma (2 papers, 2016 to 2017). "Tumor samples from 222 patients with upper tract urothelial carcinomas who were treated with radical nephroureterectomy were analyzed for the expression of seven basal/luminal immunohistochemical markers (CK5, EGFR, CD44, CK20, p63, GATA3, FOXA1)." (PMID 28632777, 2017).
urinary system cancer (2 papers, 2014 to 2023). "Except those frequent mutated genes in urinary system cancers, we also identified other less frequent mutated genes, including CSF1R (37%), NPM1 (37%), EGFR (25.9%), and NOTCH1 (22.2%)." (PMID 37515929, 2023). "Indeed, EGF/EGFR, FGFR2, KLK3, and PDGFRB were reported to play important roles in urinary system cancer development and progression." (PMID 24801713, 2014).
uterine cancer (2 papers, 2019 to 2023). Primary or metastatic malignant neoplasm involving the uterine corpus and/or the cervix. "Indeed, we also detected a MET copy-number gain in one patient (CER3) and EGFR copy-number gains in 2 patients (CER2 and CER3), both of which could be targets for novel molecular treatments for uterine cancer." (PMID 31320709, 2019).
vasculitis (2 papers, 2018 to 2024). "In cases of EGFR inhibitor-induced vasculitis, discontinuing or reducing chemotherapy or introducing oral steroids should be considered." (PMID 39881923, 2024).